IL1B (interleukin 1 beta)
Diseases named in the same sentence as IL1B in open-access papers (continued):
Sharing a sentence is not in itself a finding about the gene and the disease.
infection (continued). "Only IL-1β, IL-6, TNF and IL-4 were significantly induced by infection in the spleen (the latter also in the liver), while the production of IL-12p70 and IL-13 decreased with infection, in the liver." (PMID 23459556, 2013). "At both 17 and 48 hours after infection, 12 cytokines were elevated (G-CSF, M-CSF, IFN-γ, IL-1α, IL-1β, IL-12p70, IL-15, IL-17A, IP-10, MCP-1, MIG, and MIP-1α) in infected mice compared to placebo-inoculated mice." (PMID 23520553, 2013). "When monocytes were infected with Mtb, followed by immediate treatment with PZA at 10 or 50 μg/ml, dose-dependent reductions in the levels of pro-inflammatory molecules TNF-α, IL-6, IL-1β and MCP-1, relative to infection alone, were observed." (PMID 24015316, 2013). "We analysed the relationship between cord levels of the cytokines IL-1β and TNF-α, and parasite densities during subsequent infections." (PMID 24130857, 2013). "The results of our study also demonstrate increased expression of pro-inflammation cytokines, IL-6, IL-1β and IFN-α, following LPAIV infection in vitro." (PMID 24252391, 2013). "IL-1β, in addition to TNF-α, is thought to be involved in inflammatory responses and disease development during infection with the pathogen, but the mechanisms of IL-1β production remain poorly defined." (PMID 23357873, 2013). "The mRNA expression of IFN-γ, IL-1β, IL-6 and TNF in the frontal cortex and hippocampus of control and infected mice on day 5 post-infection were estimated by quantitative real time PCR." (PMID 24180288, 2013). "The lack of induction of classical inflammatory mediators, including IL1-β and TNF-α, during early infection has led to the suggestion that F. tularensis evades detection by host innate immune surveillance and/or actively suppresses inflammation." (PMID 23690939, 2013). "We analyzed factors induced early after infection of WT (C57BL/6) mice with Hp and observed a significant increase in IL-1β cytokine levels in the peritoneal wash, a site previously shown to contain inflammatory cells following Hp infection." (PMID 23935505, 2013). "However, presence of either IL-1α or IL-1β in single-deficient mice is sufficient to control acute M. tuberculosis infection, with restrained bacterial burden and lung pathology, in conditions where TNF deficient mice succumbed within 4 weeks with overwhelming infection." (PMID 25400917, 2013). "The infection of J774A.1 macrophages resulted in an increase in TNF-α, IL-1β, and IL-6 expression; IL-10 was downregulated during Leishmania infection, although its expression recovered compared to noninfected macrophages." (PMID 23555077, 2013). "It is important to note that the cytokines such as IL-1β and TNF-α are primarily synthesized and released by glial cells that can be activated by trauma, infection or the presence of endogenous yet abnormal protein aggregates." (PMID 24205200, 2013). "For example, IL-1β, IL-6, and TNF-α can be regarded as pro-inflammatory cytokines due to their role in early host defence against infection or disease, and in the development and progression of inflammation." (PMID 24146637, 2013). "To further check how Fas and FasL influence the cytokine and chemokine production in vivo we assessed vaginal lavages for the production of chemokines (CXCL1, CXCL9 and CXCL10) and interleukins (IL-1β and TNF-α) at 3 and 7 day of infection." (PMID 23922974, 2013). "Upon infection of BMDM and mDC with MVAΔIL-1βR, IL-1β production was observed in both cell types, but interestingly, higher IL-1β levels were detected in mDCs." (PMID 23356675, 2013). "CSFV infected cells induced to express high levels of IFN-α, IFN-β, IL-1β, IL-6 and TNF-α in a dose-dependent way within 24 h post-infection (hpi)." (PMID 24034559, 2013). "Tulobuterol (0.1 μmol/L) reduced the baseline secretion of IL-1β, IL-6, and IL-8 for 24 h before RV14 infection compared with the levels observed in cells treated with vehicle (0.001% ethanol)." (PMID 24303127, 2013).
infection (continued). "In the group with M. leprae infected macrophages co-cultured with PBMCs, the concentrations of IL-2, IL-1β and TNF-α peaked on day 1 after infection and then declined gradually." (PMID 23782413, 2013). "Of the cellular genes screened, IL-1β, IL-8 and ISG54 were significantly up-regulated by VR-2385 infection of MARC-145 cells." (PMID 23637938, 2013). "Levels of IL-1β, CXCL-1 and CXCL-2 were higher in 5-LO−/− mice 24 h after infection compared with WT mice." (PMID 23991239, 2013). "Having shown that infection of NHBE cells with HRV triggers the release of IL-1α, IL-1β and IL-18, we investigated the extent of the contribution of these cytokines to the release of other mediators by autocrine mechanisms." (PMID 23723976, 2013). "On Day 1 and Day 3 post infection, bronchoalveolar lavage fluid (BALF) protein concentration and levels of cytokines including IL6, TNFα, IL1β, Interferon-γ and IL17 were measured." (PMID 23826353, 2013). "In this study, expression levels of IL-4, IL-10, IL-13 and TNF-α were significantly up-regulated while the expression levels of IL-1β,IL-18,IFN-γ, IL-2, IL-15, IL-17F, IFN-α, IFN-β, IL-3 and CSF-1 were markedly decreased in PBMCs at all stages of infection." (PMID 24358317, 2013). "Here, we further analysed the respective roles of IL-1α and IL-1β, as compared with TNF in host response to infection by virulent M. tuberculosis but also attenuated M. bovis BCG." (PMID 25400917, 2013). "In this study, analysis from C. trachomatis infected macrophages revealed increased levels of GM-CSF, IL-1α, IL-1β, IL-6, TNF, IL-12p70, and IL-10 after a 2-day infection, with TNF, IL-6, and IL-1α being more robustly produced." (PMID 23766556, 2013). "Upon infection with the MVA derivates, even MVAΔIL-1βR was unable to stimulate IL-1β activity, as reflected by negligible reporter cell responses (right block)." (PMID 23356675, 2013). "Expression of Cxcl9 and Ccl8 was significantly up-regulated in CDC1551-infected cells at both 6 and 24 hpi, compared to infection by HN878, while Il1β was more highly up-regulated at 6 hours than at 24 hours." (PMID 22280836, 2012). "those that are highly upregulated only by infection with virulent S. flexneri (CCL4, CCL20, IFN-γ, IL-1β, IL-4, IL-6, IL-8, IL-12/23p40, IL-21, TNF-α, CAP-18, LeukoP and COX-2); ii." (PMID 22675469, 2012). "IL-1β release during infection requires NLRP3/ASC inflammasome complex that activates caspase-1, the enzyme required for processing pro-IL-1β into mature IL-1β." (PMID 22295065, 2012). "In contrast, we observed a modest trend of increased viral load at day 2 post infection in the DLN, suggesting a role for IL-1β signaling in immunity to WNV at early time-points." (PMID 23209411, 2012). "To evaluate the role of IL-1β signaling in immunity against WNV infection, we assessed infection in a well characterized murine model of WNV subcutaneous (s.c) footpad inoculation." (PMID 23209411, 2012). "We found that only a few IL-1β-expressing cells co-localized with MOMA2 at 4 and 24 hrs after infection." (PMID 23209417, 2012). "Mice that received 100 mg/kg of capsaicin showed decrease in BAL fluid IL-1β, IFN-γ and TNF-α concentration at 24 h post-infection (P = 0.007, 0.029 and 0.002, respectively)." (PMID 22427935, 2012). "Administration of MSCs led to a 50% reduction in the expression of TNFα (p = 0.01), a 34% reduction of IL1β (p = 0.02) and a 60%reduction of IL6 (p = 0.006) 7 days after infection." (PMID 22815907, 2012). "IL1 receptor antagonist (IL1RA) and IL1beta (IL1β), members of the pro-inflammatory cytokine interleukin-1 (IL1) family, play a potential role against infection and in the pathogenesis of cancers." (PMID 23049925, 2012). "Serum levels of IL-12 and IFN-γ peaked early post-infection while TNF-α, IL-6 and IL-1β levels peaked later." (PMID 22545170, 2012). "Macrophages are known to synthesize and secrete cytokines, including TNF-α, IL1-β, IL-8, IL-6, IFN-γ and others, upon infection with Mtb." (PMID 23029190, 2012).
infection (continued). "Therefore, the findings of this study suggest that previous effects of AbM that were observed against tumors and infection may be attributed to the ability of AbM to both enhance IL-1β transcription and stimulate NLRP3 inflammasome-dependent caspase-1 activation." (PMID 22844468, 2012). "Infection of 8×105 cells with 600 PFU of EMCV corresponds to the MOI below 0.001, which is insufficient to induce IL-1β secretion." (PMID 22916014, 2012). "Infection of BMDC by Lm induced secretion of IL-18 and IL-1β, which was significantly reduced upon infection with Δp60 Lm." (PMID 23028835, 2012). "Three days after oral infection of adult zebrafish with Aeromonas hydrophila harboring pRAS1, elevated expression of pro-inflammatory cytokine (TNF α, IL-1β and IL-8) and complement C3 genes in the intestine coincided with disease symptoms." (PMID 22429905, 2012). "To understand the mechanism, we compared the levels of Th1 and Th17 in the CNS of B6 mice treated with either LPS or IL-1β, along with control mice treated with PBS, following infection with TMEV at 8 days post-infection." (PMID 22985464, 2012). "Following infection of THP-1 macrophages in high extracellular [K+], M. kansasii-induced IL-1β release was significantly inhibited." (PMID 22558425, 2012). "Inflammation is the first response of the immune system to infection or irritation; inflammation is mediated by cytokines such as TNF-α, IL-1β, IL-2, IL-6, and PGE2." (PMID 22919407, 2012). "Supernatants were collected 48 hours post infection and the concentrations of TNF-α, IL-1β and IL-8 by ELISA were measured in multiple donors (N = 3)." (PMID 22727020, 2012). "In contrast, we used 1.2×106 PFU of EMCV for the infection at an MOI of 1.5, in which IL-1β secretion was clearly detected." (PMID 22916014, 2012). "After infection with each virus (104 PFU), lungs from three mice per group were collected at day 1, 3, 5 and 7 p.i. and the levels of cytokines (IL-6, IL-1β, TNF-α, IFN-γ) and chemokines (MIP-2, MIP-1α, MCP-1) in lungs were analyzed by ELISA." (PMID 22719870, 2012). "Infection of macrophages with Y. pestis KIM5 under low MOI and short contact time (20 min) results in delayed caspase-1 activation, high level of IL-1β release and cytotoxicity in a YopJ dependent manner." (PMID 22563435, 2012). "Rather, RTD-1 administration appeared to protect infected animals by reducing pulmonary inflammation and suppressing IL-1α, IL-1β, IL-6, IL-12, CXCL1 (KC), CCL2 (MCP-1), CCL3 (MIP-1α), and CCL5 (RANTES) 2–4 days post-infection." (PMID 23236475, 2012). "We found that IL-1β, TNF-α and IL-12 levels were elevated in the brains of mice on day 6-post infection, and were reduced by lovastatin treatment." (PMID 23300448, 2012). "In the current study, PR/8 infection induced an increase in TNF-α and IL-1β, well-known paracrine proinflammatory factors." (PMID 22396727, 2012). "The infection of enteric glial cells with M. tuberculosis H37Rv stimulated the production of IL-1A, TNF-α, G-CSF, GM-CSF and, to a lesser extent, of IL-1B." (PMID 22151930, 2011). "In addition, during infection with Yp-YopJCO92 orYp-YopJC172A, higher amounts of IL-1β were secreted fromIkkβΔ BMDMs as compared toIkkβF/F macrophages, consistent with the idea that theNF-κB pathway negatively regulates processing and secretion of IL-1β viacontrol of caspase-1 activation." (PMID 21533069, 2011). "In lungs infected with H9N2 LPAI virus, IL-6, IL-1β and IFN-β mRNA was found to be induced after infection in different parts of the lungs." (PMID 21314972, 2011). "Monitoring chemoattractive factors, especially those under the regulation of TGF-β (i.e. IL-1β and TNF-α), would help delineate the pro- or anti-inflammatory role of TGF-β in intramammary infection with different strains of S. aureus." (PMID 21884610, 2011). "The mutant stimulated less cytokine production in the host lungs, especially at 2 and 3 weeks of infection for both TNF-α and IL6 and at 3 and 6 weeks for IL-1β." (PMID 21687631, 2011).
infection (continued). "Infection of glial cells leads to up-regulation of CXCL10, IL-1β and IDO, and together with expression of MMP by infected astrocytes result in loss of tight junction and increased BBB permeability." (PMID 21994755, 2011). "Significant (p≤0.05) increases of IL-1β, GM-CSF, KC and RANTES were observed in the BAL fluid three days after infection." (PMID 22031815, 2011). "Early in infection (∼5 h), IL-8, MIP-1α (CCL3), GM-CSF, IL-1β, IL-17, and CD25 mRNAs were upregulated by γδ T cells." (PMID 21765931, 2011). "TNF-α, IL-1β and NOS2 are produced by macrophages in response to infection with Mtb, while IFN-γ is produced by dendritic cells and various lymphoid cells, including lymphoid cells of the innate immune response." (PMID 21364878, 2011). "Myr+ recNef treatment of primary MDMs as well as infection of MDMs with nef espressing HIV-1 pseudotypes induces the synthesis and the release of several inflammatory cytokines and chemokines (i.e. IL-1β, IL-6, TNFα, MIP-1α and MIP-1β)." (PMID 21886773, 2011). "PT also suppressed levels of IL-1β, IL-12, IFN-γ, IL-6, KC, MCP-1 and TNF-α in the airways after PR8 infection." (PMID 21533103, 2011). "At 8 hours and, more so, at 24 hours post-infection, cultured BMDM infected with CP secreted IL-1β in a Casp1-dependent manner." (PMID 21731762, 2011). "Efficient activation and differences in transcript levels of IL-1β and IL-8 mRNA were already observed at a S. suis to PBMC ratio of 1∶1 at the start of infection and as early as 2 and 4 h post infection." (PMID 21811583, 2011). "In the first, immune response genes such as IL-6, IL-1α, IL-1β and IFN-β were upregulated one hour following infection but this upregulation rapidly returned to baseline and was not sustained." (PMID 21789257, 2011). "Fever is induced by pro-inflammatory cytokines such as interleukin (IL)-1β, IL-6, and tumor necrosis factor (TNF)-α during infections." (PMID 21989210, 2011). "The production of IL-1β, IFN-α, IL-10, TGF-β, IL-4 and TNF-α by the nervous tissues of infected animals increased significantly at different times after infection." (PMID 21813860, 2011). "Only CXCL10 expression was significantly attenuated in TLR4 mutant mice at day 3 post-infection, whereas the majority of mediators, including CCL2, CXCL1, and IL-1β were similar between TLR4 mutant and WT mice across all time points examined." (PMID 21496301, 2011). "Transcript levels of IL-1β in CTC+CR mice remained lower relative to CR treatment mice at both the peak and late infection periods." (PMID 21943280, 2011). "Pro-inflammatory cytokines including IL-1β and TNF-α were markedly elevated and sustained in plasma of SIV infected macaques thorough 21 days of infection." (PMID 21464951, 2011). "IL-1β (9–10-fold) levels were significantly depressed in naïve and LVS-immunized mice by day 2 of infection." (PMID 20967278, 2010). "By 48 h post-infection the levels of both cytokines had decreased but remained significant with concentrations of TNF-α = 45 ± 12 pg/ml, and IL-1β = 104 ± 12 pg/ml." (PMID 20565713, 2010). "Flow cytometry data demonstrated that WNV-induced SK-N-SH cells apoptosis (25.8%) was significantly suppressed in the presence of neutralizing antibodies against IL-1β (12.3%) and TNF-α (13.5%) (p < 0.05) at day 2 after infection." (PMID 21034511, 2010). "Mice infected with CO92ΔyopH elicited a robust pro-inflammatory cytokine response at 24 h post-infection, characterized by 349 ± 43 pg/ml of TNF-α and 461 ± 35 pg/ml of IL-1β in the BALF of these mice 24 h post-infection (p = 0.001 in comparison to CO92)." (PMID 20565713, 2010). "On the other hand, significant amounts of soluble IL-1β, -6 and TNF-α were detected in supernatant from infected cells at day 2 and 3 after infection (p < 0.05)." (PMID 21034511, 2010). "In this study, our data suggests that YopH inhibits the production of IL-1β and TNF-α during the first 24 hours post-infection." (PMID 20565713, 2010).
infection (continued). "We propose that upon infection with S. pneumoniae, PLY, in synergy with pneumococcal PAMPs promotes the secretion of proinflammatory cytokines, particularly IL-1β, that promote an inflammatory response and mediate protective immunity." (PMID 21085613, 2010). "After 24 h, OppD-KO infection led to lesser amounts of TNF-α, IL-1β and IL-6 production in macrophages compared to the wild type." (PMID 20808924, 2010). "During infection with the virulent Mtb strain H37Rv, THP-1 cells with shPYCARD or shNLRP3 secreted significantly less IL-1β than their scrambled controls." (PMID 20808838, 2010). "rhodesiense-infected mice treated with cordycepin and deoxycoformycin starting 20 days after infection contained diminished levels of IFN-γ, IL-1β, IL-6 and TNF-α mRNA compared to untreated infected controls when measured 10 days after treatment." (PMID 19652702, 2009). "We thus next examined the levels of TNF, IL-1β, IL-2, IL-6, IL-10, and MCP-1 (also known as CCL2) in human PBMC infected by CDC1551, HN878, and HN878 pks1-15::hyg 2 and 4 days post-MTb infection." (PMID 19568431, 2009). "High levels of IL-1β and TNF-α have also been reported to be released from in vitro explant model upon infection with CT serovar E." (PMID 19698128, 2009). "All genes play major roles in immune response during infection including cytokines (IL8, IL6, IL10, IL1B, and TNF) and SAA3 (an acute-phase protein), as well as PMN adhesion selectin-L (SELL) and LYZ (involved in anti-microbial defense)." (PMID 19925655, 2009). "At 24 h post infection, pulmonary cytokine and chemokine levels were lower in TLR2 KO mice, significantly so for IL-1β (P < 0.05)." (PMID 17711480, 2008). "In mice infected with the ΔsigC mutant, the levels of TNF-α, IL-1β, IL-6 and IFN-γ began to drop 14 days post infection and persisted throughout the study while a significant reduction in CCL-2 and CCL-5 levels was detected 70 days after infection." (PMID 18798983, 2008). "In LPS-stimulated whole blood, a significant reduction was observed on IL-1β and TNF-α production in the TB group, representing a reduced capacity of immune cells to react to an infection ex vivo." (PMID 19018259, 2008). "To further investigate the role of TLR2 during infection with S. pneumoniae PLN, we determined TNF-α, IL-1β, IL-10, MIP-2, KC and MPO levels in whole lung homogenates obtained 24, 48 and 72 h after inoculation." (PMID 17711480, 2008). "A variety of cytokines and chemokines were measurable during infection including: GRO, IL-1β, IL-6, IL-10, IL-12, GM-CSF, TNFα, MDC, and IL-8." (PMID 17257430, 2007). "The cytokines secreted by phagocytes in response to infection include tumor necrosis factor (TNF)-α, IL-1β, IL-6, IL-8 as well as IL-10." (PMID 16280065, 2005). "The cytokines secreted by phagocytes in response to infection include TNF-α, IL-1β, IL-6, IL-8 and IL-10." (PMID 16280065, 2005). "Levels of inflammatory cytokines IL‐1β, IL‐6, IL‐8, IL‐10, IL‐12/23p40, TNF‐α, and HMGB1 were significantly upregulated by infection with S. Typhimurium in the LT2 group." (PMID 41474380, 2026). "In the current study, Spearman correlation analysis shows that the abundance of Proteobacteria exhibited a positive correlation with rectal temperature at both 12 and 24 h post-infection, as well as with serum TNF-α levels and jejunal IL-1β and TNF-α mRNA levels." (PMID 41547922, 2026). "We found that RSV-induced plasma membrane rupture and IL-1β release were unaffected by GSDMD knockout, but abolished upon GSDME deletion, indicating that RSV promotes GSDME-dependent pyroptosis for IL-1β secretion in late infection." (PMID 41576161, 2026). "Additionally, we observe elevated levels of specific cytokines, including IL-17, IL-6, IL-1β, and TNF-α, which collectively contribute to inflammation and tissue damage in the lungs during infection." (PMID 41597746, 2026).